SLC16A1 (solute carrier family 16 member 1)
Diseases named in the same sentence as SLC16A1 in open-access papers (continued):
Sharing a sentence is not in itself a finding about the gene and the disease.
tumor (continued). "Following the co-expression and network analyses, this signature was found to be enriched for genes involved in the regulation of the stroma component of the tumor (TDO2, STEAP1) as well as Treg cells (SLC16A1, PRKAB1) and myeloid cell (APOBEC3A, MERTK, SNX29) subsets." (PMID 36216827, 2022). "In summary, while PPARA, VDR, SLC16A1 and PAPSS2 supply the building blocks to synthesize macromolecules, GPX1 provides redox defense to counteract oxidative stress produced as a consequence of the high proliferation rates of tumor cells." (PMID 35565211, 2022). "Additionally, studies have reported that SLC16A1, besides its function as a proton transporter, can also induce epithelial-mesenchymal transition in tumor cells by activating the HGF/C-MET pathway, thereby promoting tumor invasion and metastasis." (PMID 38911368, 2024). "Conversely, the expression of SLC16A1 and SLC16A7 genes —encoding MCT1 and MCT2 lactate transporters, respectively—as well as of GJA1 (data not shown) encoding connexin 43 and responsible of lactate diffusion, does not differ between the two tumour subtypes." (PMID 37198319, 2023). "For instance, SLC16A1 and BSG, belonging to cluster 1 and playing vital roles in energy metabolism, are up-regulated in a variety of cancer types and could promote tumor growth and aggressiveness through the Warburg effect." (PMID 35580989, 2022). "Mediators of increased acid extrusion in tumor cells include the Na+/H+ exchanger NHE1 (SLC9A1), the Na+,HCO3− cotransporter NBCn1 (SLC4A7), the lactate,H+ cotransporters of the monocarboxylate transporter family, MCT1 and MCT4 (SLC16A1 and −3), and, in some cells, V-type H+-ATPases." (PMID 27266704, 2016). "We found that the majority of genes co‐expressed with SLC16A1 were genes correlated with normal biological processes of cells, while genes co‐expressed with SLC16A3 were functionally clustered in the categories considered relevant for tumour progression and development." (PMID 25875424, 2015). "In contrast, other tumor areas exhibiting high expression of TMPRSS11B together with BSG and SLC16A1 were largely negative for KLF4 expression." (PMID 40508207, 2025). "Among most of these tumor types, a negative correlation between gene methylation and mRNA expression was revealed by calculating the Spearman correlation, including HIF1A, SLC16A1, UEVLD, SLC16A8, PFKFB2, LDHB, and SLC16A3." (PMID 37122693, 2023). "Tumor regions without increased 18F-FDG uptake showed increased SLC13A5 and SLC16A1 expression, whereas tumors with increased 18F-FDG uptake showed high SLC2A1 and HIF1α." (PMID 35884416, 2022). "The difference in the expression of the five ADME genes (SLC16A1, SLC7A5, SLCO1B1, CYP17A1, and ABCC8) between tumor and normal tissues was significant and was closely correlated with the survival of patients with NSCLC." (PMID 34522968, 2021). "However, it was shown that its pro-tumour function is mostly due to its interaction with monocarboxylate transporters (MCTs), such as MCT1 (also known as SLC16A1) and MCT4 (also known as SLC16A3), rather than MMPs." (PMID 35054026, 2022).
cancer (94 papers, 2013 to 2026). A tumor composed of atypical neoplastic, often pleomorphic cells that invade other tissues. "This is underscored by the fact that in SLC16A1/BSG-expressing but TMPRSS11B-deficient cancer cells, the nuclear expression levels of reprogramming factors such as KLF4 are elevated, a condition identified as a hallmark of reverse Warburg cells." (PMID 40508207, 2025). "By contrast, under glucose shortage, uptake of lactate provides an essential advantage for those cancer cells expressing SLC16A1, which, in contrast to SLC16A3, also drives the import of lactate." (PMID 40508207, 2025). "Among the MCT family, MCT1 and MCT4 (encoded by SLC16A1 and SLC16A3, respectively) are most relevant in cancer, facilitating lactate metabolism and pH homeostasis." (PMID 40433363, 2025). "Utilizing bioinformatics analysis, we pioneered the identification of the clinical significance of SLC16A1 in this type of cancer." (PMID 38911368, 2024). "Previous research has already highlighted the critical role of SLC16A1 in the development and progression of various cancers." (PMID 38911368, 2024). "In our current study, we first identified the expression of SLC16A1 in the transcriptome and proteome of human tumors and found abnormal expression of SLC16A1 in various human cancers." (PMID 38911368, 2024). "We found that SLC16A1's mRNA expression levels were generally elevated across a variety of human cancers." (PMID 38911368, 2024). "Not only that, we also employed additional algorithms to evaluate the relationship between SLC16A1 expression and the level of immune cell infiltration across various cancers." (PMID 38911368, 2024). "Previous studies have confirmed that SLC16A1 is expressed in almost all human tissues and overexpressed in many cancers, indicating poor prognosis." (PMID 38539084, 2024). "Intriguingly, we also observed a compelling correlation between elevated SLC16A1 expression and reduced overall survival, indicating its potential as a prognostic indicator in cancer patients." (PMID 38730450, 2024). "Lactate transport in cancer is mainly facilitated by monocarboxylate transporters (MCTs), particularly MCT1 (encoded by SLC16A1), which play a vital role in transporting lactate and protons across the cell membrane." (PMID 38730450, 2024). "Although some studies have investigated the expression of SLC16A1 in human cancers, the information available remains incomplete." (PMID 38911368, 2024). "Research has shown that SLC16A1 is distributed in almost all human tissues and is overexpressed in many cancers." (PMID 38169083, 2024). "This process generates a high amount of lactate, which must be expelled from cancer cells through SLC16A1 to avoid cytotoxicity." (PMID 38911368, 2024). "The FISH data showed that hsa_circ_0013561 (circ-SLC16A1) expression was relatively increased in NSCLC tissue as compared with the para-carcinoma tissue and mainly located in cytoplasm." (PMID 38539084, 2024). "The solute carrier family 16 member 1 (SLC16A1) belongs to the proton-coupled monocarboxylate transporter protein family and is a key transcription factor regulating cancer progression and metastasis." (PMID 36894874, 2023). "Cancer cells avoid this detrimental effect by promoting the efflux of lactic acid via the H+-coupled monocarboxylate transporters MCT1 (SLC16A1) and MCT4 (SLC16A3), both of which are upregulated in cancer." (PMID 36765717, 2023). "In particular, gene-expression analyses show that all derivative cells with high anchorage-independent growth or invasive activity show increased expression of SLC16A1, a phenomenon that contributes to the glycolytic phenotype of cancer cells." (PMID 36302783, 2022). "Some miRNAs have shown to modulate SLC16A1 expression and influence lactate transport in cancer cells." (PMID 35755805, 2022). "SLC16A1 inhibition blocks tumor growth by increasing glucose use by oxidative cancer cells, which results in hypoxic cancer cell death due to glucose starvation." (PMID 35755805, 2022).
cancer (continued). "SLC16A1 and SLC16A3 are overexpressed and associated with poor prognosis in cancers, such as pancreatic cancer." (PMID 35755805, 2022). "Cancer cells can increase carcinogenicity and invasion by overexpressing SLC16A1 and transporting lactic acid inward." (PMID 36698888, 2022). "Next, we performed a survival analysis of SLC16A1-14 in pan-cancer (> 5 normal controls) and found that the SLC16 family can guide the prognosis of many tumors." (PMID 34424811, 2021). "To confirm these data, we tested the expression of the monocarboxylate transporter 1 (MCT1 or solute carrier family 16 member 1 (Slc16a1)) that has been already demonstrated to provide metabolic fuels to cancer cells." (PMID 34440835, 2021). "In a similar manner, it is also possible that SLC38A5 and the H+-coupled lactate transporter MCT1 (SLC16A1) are functionally coupled in cancer cells via H+." (PMID 33806675, 2021). "The PPI-based enriched GO terms strongly suggested that SLC16A1 is involved in cancer cell proliferation and the cell cycle." (PMID 32355273, 2020). "Our major findings for SLC16A1 regarding its participation in gene networks showed that SLC16A1 was a key controller of the cell cycle and mitosis, strongly suggesting its oncogene role in promoting cancer cell proliferation." (PMID 32355273, 2020). "To address this issue, we have conducted correlation analyses between the expression levels of SLC16A1 and all the up-regulated genes in each cancer type, followed by pathway-enrichment analyses of these genes." (PMID 31071451, 2019). "The only group of genes considered here has the same behaviors between cancer vs. NPCs is SLC16A1/3, with their expressions up-regulated in both cancer and the activated NPCs." (PMID 31071451, 2019). "In sum, expressions of the acid-loading transporter genes are largely up-regulated, whereas expressions of the acid-extruding transporter genes are down-regulated in cancer vs. controls except for SLC16A1/3." (PMID 31071451, 2019). "Lactate efflux from cancer cells is mediated primarily by the monocarboxylate transporters MCT1 (SLC16A1) and MCT4 (SLC16A3), both of which transport lactate together with a proton across the cell membrane." (PMID 29809145, 2018). "The migratory response of cancer cells has also been correlated with increased SLC16A1 (MCT-1) expression." (PMID 27812189, 2016). "Nevertheless, there are several case reports documenting the use of this compound in cancer patients, underscoring the importance of understanding how SLC16A1 gene expression is regulated." (PMID 27729975, 2016). "One of the additional genes affected was monocarboxylate transporter 1 (SLC16A1, encoding the protein MCT-1), a known lactate transporter observed to be upregulated in many cancers." (PMID 27729975, 2016). "Tumor cells also contain high levels of the bidirectional lactate transporter MCT1 (encoded by SLC16A1), which facilitates the excretion of excess lactate produced through glycolysis, while MCT4, commonly expressed in many cancers, functions almost exclusively as a lactate exporter." (PMID 41547734, 2026). "Thus, SLC16A1-expressing cancer cells, e.g., in PDAC, acquire a reverse Warburg metabolism preferentially in the absence of TMPRSS11B expression, as supported by our experimental data." (PMID 40508207, 2025). "SLC16A1 plays an important role in cancer metabolism, promoting cancer progression and metastasis." (PMID 40822284, 2025). "In summary, SLC16A1 has been reported to play a pivotal role in the development and progression of a considerable number of human cancers, making it an important subject of cancer research and a potential therapeutic target." (PMID 38911368, 2024).
cancer (continued). "Additionally, ouabain has been confirmed to inhibit the SLC16A1‐mediated uptake of lactate, a key product of glycolysis and a process favored by cancer cells due to the Warburg effect." (PMID 39350574, 2024). "Given the central role of SLC16A1 in cancer cell metabolism, it may serve as a potential target for cancer therapy." (PMID 39350574, 2024). "Notably, the analysis revealed a significant upregulation of SLC16A1 in 12 different malignancies, indicating its potential involvement in tumorigenesis and suggesting a broader role across various cancer types." (PMID 38730450, 2024). "Therefore, we initially utilized bioinformatics methods to analyze the mRNA and protein level expression of SLC16A1 in human cancers." (PMID 38911368, 2024). "Despite extensive research demonstrating the critical role of SLC16A1 as an oncogene in various cancers, its role in the progression and treatment of CCA remains unclear." (PMID 38911368, 2024). "SLC16A1 and SLC16A3, also known as SLC16A1/3, have considerable expression levels in cervical malignancies and are closely linked to the malignant characteristics of the cancer." (PMID 39229578, 2024). "In cancer, SLC16A1 has a role in lactate shuttling between cells, depending on their demand." (PMID 34298852, 2021). "Moreover, over two thirds of the pathways that are most commonly shared by different NPCs are also growth or development related, hence suggesting our prediction that the cellular roles of SLC16A1 is different in cancer and in NPCs." (PMID 31071451, 2019). "Thus, proteolytic cleavage of the Ig-C2/Ig-I domain of BSG may lead to an altered conformation of the BSG/SLC16A3 and BSG/SLC16A1 conformation, supporting a forced export of lactate as a prerequisite for enhanced glycolysis and cancer cell growth." (PMID 40508207, 2025). "Targeting SLC16A1 may, therefore, prove to be a promising therapeutic strategy for some cancers." (PMID 36698888, 2022). "Interestingly, oncogenic KRAS mutations were shown to increase glucose uptake in cancer cells and lactate production through upregulation of glycolytic genes encoding glucose transporter SLC2A1/GLUT1 and the monocarboxylate transporters SLC16A1/MCT1, SLC16A7/MCT2, and SLC16A3/MCT4." (PMID 34003553, 2021). "In addition, the expression of either SLC16A1 or SLC16A3 is up-regulated in the cancer tissues of all 14 cancer types except for COAD (see Materials and Methods for definition), which is known to have weak Warburg effect and hence generally not detected via PET/CT." (PMID 31071451, 2019). "Beyond PDAC, clinical and preclinical studies in other cancers have demonstrated the efficacy of targeting SLC transporters such as SLC7A5 (LAT1), SLC16A1 (MCT1), and SLC6A14 in suppressing tumor growth and modulating therapeutic resistance." (PMID 40282424, 2025). "Among these four MCTs, only MCT1 (SLC16A1) and MCT4 (SLC16A3) have been shown to be most relevant to cancer cells." (PMID 38339256, 2024). "Further in vitro and in vivo, experimental results have demonstrated that the knockdown of SLC16A1 effectively inhibits the growth of CCA cells, affirming its significant role as an oncogene in this type of cancer." (PMID 38911368, 2024). "Additional candidates are reported to be involved in cancer prognosis and progression, including TSPAN11, NKX6-1, and SLC16A1." (PMID 36975205, 2023). "Among the MCTs, MCT1 (SLC16A1) and MCT4 (SLC16A3) have been most extensively studied in cancer, as these transporters play important role in lactate transport in cancer cells to support their survival." (PMID 36839686, 2023). "Lactic acid exporters SLC16A1 and SLC16A3 have also been suggested to play a role in intracellular alkalization in cancer." (PMID 35787947, 2023). "During metabolic symbiosis, SLC16A1 is involved in the influx of lactic acid into oxidative cancer cells, while SLC16A3 is involved in the efflux of lactate from glycolytic cancer cells." (PMID 35755805, 2022).
cancer (continued). "It is noteworthy, however, that RNF128, SLC16A1, SPRED1, TNRC6B, and TTK are novel in that they are found only among the candidate cancer genes identified by forward genetic screens in mice or among the genes whose expression changes in cancer." (PMID 33427197, 2021). "Thus, TMPRSS11B expression is reciprocal to the highly malignant reverse Warburg cells expressing SLC16A1 and BSG, giving rise to relapse-forming and also metastasizing cancers." (PMID 40508207, 2025). "miR-7-5p/ABCC1/SLC7A5, miR-107/RAD51, miR-124-3p/ABCC4/SLC16A1/MGMT, miR-212-3p/ABCG2, miR-381-3p/GJA1 and miR-485-3p/SLC40A1 may modulate pathways that confer chemoresistance to cancer cells." (PMID 40061896, 2025). "However, AZD3965, an inhibitor of SLC16A1 (MCT1), is a notable new drug that is currently undergoing phase III clinical trials in cancer patients." (PMID 39218897, 2024). "Overall, our research provides new insights into the role of SLC16A1 in CCA cells, which may promote the development of new therapeutic strategies to overcome the drug resistance of CCA cells to existing cancer treatments." (PMID 38911368, 2024). "AL357055.3(lnc-SLC16A1-2:1) has not been reported, but its homologous protein SLC16A1 is a confirmed poor prognosis marker in various malignant tumors, possibly due to its involvement in glycolysis and glucose metabolism synthesis." (PMID 37837543, 2023). "One popular model is that Na+/H+ exchangers, particularly NHE1 (SLC9A1), are the main reason for the reversal of pHi and pHe in cancer tissues, along with monocarboxylate-H+ efflux cotransporters MCT1 (SLC16A1) and MCT4 (SLC16A3) and carbonic anhydrases for CO2 hydration." (PMID 35787947, 2023). "MCT1 (SLC16A1) is ubiquitously expressed and has high affinity for serum lactate as the cellular lactate importer, whereas MCT4 (SLC16A3) is strongly expressed in glycolytic cancer tissues for intracellular lactate export." (PMID 36615660, 2022). "Among the 14 MCT family members, MCTs 1 and 4 (SLC16A1 and SLC16A3, respectively), the most commonly upregulated isoforms in cancer, can either uptake lactate for energy purposes or export it to maintain homeostasis, and both have been linked to multidrug resistance as well as poor prognosis." (PMID 35011413, 2021). "Within the favorable genes, UNC13B, and SFXN2 cover nine cancer types and in the same way, SLC2A1, PLS3, SLC16A1, and SLC16A3 within the unfavorable set of genes and could serve as novel target structures." (PMID 32599841, 2020). "MCT1 (SLC16A1) and MCT4 (SLC16A3) are important in cancer metabolism." (PMID 31201333, 2019). "In parallel, we examined the effects of ATGL on glycolysis: lower glucose uptake, extracellular lactate concentration, and decreased expression of SLC2A1/GLUT1 and SLC16A1/MCT1, the glucose and lactate transporters commonly found altered in different types of cancer, were remarked." (PMID 30367149, 2019). "In addition, SLC7A5 (regulated by miR-7-5p), SLC16A1 (regulated by miR-124-3p), and SLC40A1 (regulated by miR-485-3p) genes, belong to the transmembrane solute transport (SLC) and are involved in chemoresistance in many of the cancers studied here." (PMID 40061896, 2025). "Moreover, reverse Warburg areas in PDAC patient-derived cancer tissues were identified by high SLC16A1 and BSG expression but absence of TMPRSS11B expression." (PMID 40508207, 2025). "Being essential for the heterogeneity of many malignant tumors, these reverse Warburg cancer cells might differentially contribute to malignant progression depending on the presence of SLC16A1 and BSG as well as the absence of TMPRSS11B." (PMID 40508207, 2025). "The results from our study showed that SLC16A1 and SLC16A3 RNA level expression was significantly increased in PAAD samples compared with normal tissues according to the Oncomine multiple pan-cancer analysis, indicating that these two genes widely participate in cancer biological behavior." (PMID 32355273, 2020).
cancer (continued). "Therefore, we conclude that lactic acid secretion by SLC16A1 is most likely not related to intracellular pH homeostasis, instead it serves a protective role for cancer." (PMID 31071451, 2019).
infection (3 papers, 2017 to 2022). The state of being infected such as from the introduction of a foreign agent such as serum, vaccine, antigenic substance or organism. "No significant changes in the levels of expression of podocyte marker genes (WT1, PODXL, NPHS1, NPHS2, and MAFB) or for tubular marker genes (SLC3A1 and SLC16A1) were found after infection comparing WT and ACE2 KO kidney organoids." (PMID 35561674, 2022).